TRIM44 (tripartite motif containing 44)
Description:
May play a role in the process of differentiation and maturation of neuronal cells (By similarity). May regulate the activity of TRIM17. Is a negative regulator of PAX6 expression.
Synonyms: DIPB; MC7; AN3; HSA249128
Tractability: Antibody: the Human Protein Atlas places it where antibodies can reach. PROTAC: ubiquitination databases record sites on it.
Gene: Protein-coding gene on chromosome 11 (35,662,537 to 35,818,007, forward strand). Ensembl gene ENSG00000166326.
Subcellular location (Human Protein Atlas): Vesicles; Plasma membrane
Gene Ontology:
Molecular function: protein binding; ubiquitin protein ligase activity; zinc ion binding
Biological process: negative regulation of protein K48-linked ubiquitination; positive regulation of cytokine-mediated signaling pathway; positive regulation of defense response to virus by host; positive regulation of DNA-templated transcription; positive regulation of non-canonical NF-kappaB signal transduction; protein stabilization; regulation of gene expression; innate immune response
Cellular component: cytoplasm
Genetic constraint (gnomAD): Loss-of-function variants: 13 observed, 36.86 expected, observed/expected ratio (o/e) 0.35, 90% interval 0.23 to 0.56. The upper end of that interval is the gene's LOEUF score, 0.56, which puts it in group 2 of 6, group 1 being the genes least tolerant of losing a copy. Missense variants: 426 observed, 451.74 expected, observed/expected ratio (o/e) 0.94, 90% interval 0.87 to 1.02. Synonymous variants: 175 observed, 163.26 expected, observed/expected ratio (o/e) 1.07, 90% interval 0.95 to 1.22.
Gene-disease validity (ClinGen):
ClinGen rates the evidence that TRIM44 causes each of these diseases.
aniridia 3 (autosomal dominant): Limited.
Homologues: Orthologues: chimpanzee TRIM44 (100% identical), macaque TRIM44 (97% identical), rabbit TRIM44 (94% identical), mouse Trim44 (92% identical), pig TRIM44 (91% identical), rat Trim44 (91% identical), dog TRIM44 (84% identical), guinea pig TRIM44 (74% identical), tropical clawed frog trim44 (31% identical), zebrafish trim44 (25% identical). Paralogues in human: MID2 (16% identical), TRIM25 (15% identical), MID1 (15% identical), TRIM55 (15% identical), TRIM54 (15% identical), TRIM27 (14% identical), TRIM4 (14% identical), TRIM46 (14% identical), TRIM5 (14% identical), TRIM63 (14% identical), TRIM7 (14% identical), TRIM77 (14% identical), and 68 more.
Diseases named in the same sentence as TRIM44 in open-access papers:
TRIM44 is named in the same sentence as 53 diseases in open-access papers, as found by Europe PMC text mining. Sharing a sentence is not in itself a finding about the gene and the disease. The quoted sentences say what the papers report.
lung carcinoma (20 papers, 2016 to 2025). "miR-192-5p, which is associated with TRIM44, its upregulation suppressed tumor behaviors in lung cancer cells." (PMID 34655361, 2021). "In the present study, we demonstrated that reduced miR-192-5p and increased TRIM44 levels were associated with the proliferation, migration and invasion of lung cancer." (PMID 31873114, 2019). "Here, we propose a model of the molecular mechanism underlying the effects of TRIM44 on lung cancer progression." (PMID 27058415, 2016). "Although TRIM44 facilitates the migration and invasion of human cancer cells, the mechanisms underlying TRIM44 activity during lung cancer metastasis are unclear." (PMID 27058415, 2016). "Moreover, miR - 192 - 5p is downregulated in lung cancer tissues, and its decreased expression is correlated with increased TRIM44 levels, which are associated with augmented proliferation, migration, and invasion of lung cancer cells." (PMID 40837012, 2025). "TRIM44 is involved in the virus-mediated immune response, neurodegenerative diseases, developmental disorders and malignant diseases, including lung cancer 12-15." (PMID 35541909, 2022). "TRIM44 displayed an upregulated expression in lung cancer cells, substantially facilitating invasion and migration of cancer cells." (PMID 35912155, 2022). "For example, during bone metastasis in lung cancer, miR-192-5p impedes cell proliferation and migration, as well as invasion by targeting the inhibition of TRIM44 expression." (PMID 36193069, 2022). "MiRNA-143-3p promotes metastasis of lung cancer cells to the brain by stimulating N6-methyladenosine, while miRNA-192-5p prevents metastasis of lung cancer cells to bones by negatively regulating TRIM44." (PMID 35885514, 2022). "In 2019, Zou and coworkers demonstrated that the expression of miR-192-5p is downregulated in the serum of patients with lung cancer and lung cancer cell lines, while the expression of tripartite motif 44 (TRIM44) shows an opposite tendency." (PMID 33708127, 2021). "For example, miR-192-5p inhibited lung cancer bone metastasis by negatively modulating TRIM44 expression." (PMID 34486645, 2021). "Accumulating evidence has revealed that TRIM44 enhances the proliferation, migration, and invasion of lung cancer." (PMID 31873114, 2019). "our results suggest that miR-192-5p inhibited the proliferation, migration and invasion of lung cancer through TRIM44." (PMID 31873114, 2019). "It was observed that co-transfection with miR-192-5p mimics and TRIM44 reversed some of the effects of TRIM44 on lung cancer cell behaviours." (PMID 31873114, 2019). "The mechanism of the downstream pathway through which miR-192-5p can inhibit lung cancer by targeting TRIM44 should be explored." (PMID 31873114, 2019). "Our observations support that upregulation of miR-192-5p suppresses lung cancer cell proliferation, migration and invasion via targeting TRIM44." (PMID 31873114, 2019). "As such, we propose that miR-192-5p upregulation in patient serum and lung cancer cell lines inhibits lung cancer metastasis, possibly by downregulating TRIM44." (PMID 31873114, 2019). "The crosstalk between TRIM44 and the NF-κB signaling pathway has been reported in malignancies such as lung cancer cells and hepatic cancer cells." (PMID 28885545, 2017). "To date, several studies have reported that TRIM44 contributes to the progression of human malignancies such as lung cancer, esophagus and gastric cancers, breast cancer, hepatic cancer, and testicular germ cell tumor." (PMID 28885545, 2017). "In terms of TRIM44, activation of the NF-κB signaling pathway has been reported in lung cancer cells and hepatic cancer cells." (PMID 28885545, 2017). "Western blot analysis detected TRIM44 protein in most of the lung cancer cell lines examined (10/12 cell lines)." (PMID 27058415, 2016). "Together, the in vitro and in vivo experimental data allowed us to propose a new model for how TRIM44 promotes lung cancer progression." (PMID 27058415, 2016).
lung carcinoma (continued). "Another report indicated that TRIM44 could activate the NF-κB pathway to promote lung cancer cell migration and invasion." (PMID 32503466, 2020). "In addition, our data revealed that TRIM44 mRNA expression was significantly upregulated in lung cancer cells compared with that in BEAS-2B cells, which was consistent with the western blot analysis." (PMID 31873114, 2019). "Consistent with the previous report, TRIM44 facilitates the migration and invasion of human lung cancer cells via the NF–κB signaling pathway and in another preclinical study, while TRIM44 promotes proliferation and metastasis in non–small cell lung cancer via mTOR signaling pathway." (PMID 30792262, 2019). "Furthermore, our results suggest that miR-192-5p inhibited the proliferation, migration and invasion of lung cancer through TRIM44." (PMID 31873114, 2019). "Additionally, another report demonstrated that TRIM44 facilitated the migration and invasion of cancer cells via activating the NF‐κB pathway in lung cancer." (PMID 29446253, 2018). "Also, we found that TRIM44 is required to maintain the aggressive and malignant phenotypes of lung cancer cells, and that TRIM44 increases EMT and cell cycle progression in tumor cells by activating the mTOR pathway." (PMID 27058415, 2016). "Likewise, miR-192 represses the bone metastasis of lung cancer by targeting TRIM44." (PMID 33097010, 2020). "In lung cancer, several reports have recognized miR-498-5p as a tumour suppressor by targeting HMGA2, tripartite motif containing 44 (TRIM44) or forkhead box O3 (FOXO3)." (PMID 37667197, 2023). "However, the biological function of TRIM44 in lung cancer bone metastasis remains unclear." (PMID 31873114, 2019). "Overexpression of TRIM44 induced the epithelial-to-mesenchymal transition (EMT) and increased the metastatic potential of lung cancer cells." (PMID 27058415, 2016). "Overexpression of TRIM44 induced EMT and increased the metastatic potential of lung cancer cells." (PMID 32503466, 2020). "TRIM44 overexpression has been reported in a diversity of tumors, including prostate cancer, gastric cancer, hepatocellular carcinoma (HCC), intrahepatic cholangiocarcinoma, testicular germ cell tumor, lung cancer, and esophageal carcinoma." (PMID 30792262, 2019).
gastric cancer (12 papers, 2016 to 2025). A primary or metastatic malignant neoplasm involving the stomach. "TRIM44 overexpression was confirmed to be associated with the malignant phenotype in gastric cancer, lung adenocarcinoma, and ovarian cancer." (PMID 41357604, 2025). "The clinical analysis of gastric cancer samples showed that high TRIM44 expression was associated with advanced TNM stages, reduced T-cell infiltration, and poor overall survival." (PMID 39768197, 2024). "Enhanced expression of TRIM44 was associated with an advanced type of macroscopic appearance, lymphatic invasion, and higher recurrence rate, and poor prognosis of patients with gastric cancer." (PMID 30792262, 2019). "A study in gastric cancer biopsies shows that the expression of the TRIM44 protein is inversely correlated with the expression of LOXL2." (PMID 40906383, 2025). "In gastric cancer, it has been shown that TRIM44, an E3 ubiquitin ligase, regulates the stability of the LOXL2 protein, a key factor for crosslinking collagen and important for remodeling the ECM, thus regulating tumor immunity." (PMID 37296972, 2023). "They suggest the TRIM44/LOXL2 complex as a potential biomarker for gastric cancer prognosis and as a novel immunotherapy target." (PMID 37296972, 2023). "Another negative regulator of LOXL2 is the tripartite motif-containing protein 44 (TRIM44), a regulator of tumour immunity in gastric cancer." (PMID 37762708, 2023). "Overexpression of TRIM44 is reported in 16% of epithelial cancers including gastric cancers and breast cancers." (PMID 30089913, 2019). "Elevated TRIM44 expression in gastric cancer correlates with lymph node invasion and recurrence and is a predictor of poor survival." (PMID 27058415, 2016). "Meanwhile, cultured cell experiments revealed that mTOR signaling could be one of the major enriched pathways in gastric cancer cells with TRIM44 overexpression." (PMID 28885545, 2017). "Furthermore, TRIM44 was found to be upregulated in human gastric cancer patients either." (PMID 39768197, 2024). "This study shows that TRIM44 regulates the stability of LOXL2 and thus modulates the ability of LOXL2 to remodel the extracellular matrix in gastric cancer." (PMID 40906383, 2025). "Specifically, TRIM44 mediated the ubiquitination and subsequent degradation of Lysyl Oxidase Like 2 (LOXL2), thus impacting extracellular matrix remodeling and influencing tumor immunity in gastric cancer." (PMID 39768197, 2024). "Overexpression of TRIM44 contributes to malignant outcome in gastric carcinoma, and forebodes a worse OS than those with non-expressing tumors." (PMID 30792262, 2019). "A previous study showed that knocking down TRIM44 expression impaired the proliferation of human gastric cancer cells in vitro, but it did not fully elucidate the mechanism via which TRIM44 promotes cancer cell proliferation." (PMID 27058415, 2016). "TRIM44 may function as a “USP-like TRIM” and promote cancer development by regulating de-ubiquitination and stabilization of oncogenes, and its overexpression could contribute to malignant outcomes in gastric cancer." (PMID 35004288, 2021).
breast cancer (9 papers, 2014 to 2024). A primary or metastatic malignant neoplasm involving the breast. "Upregulated TRIM44 is also associated with a poor prognosis in testicular germ cell tumor, esophageal squamous cell carcinoma, and breast cancers." (PMID 30089913, 2019). "TRIM44 knockdown caused attenuated proliferation and migration of breast cancer cells, suggesting that TRIM44 may be a potential therapeutic target for breast cancer." (PMID 28885545, 2017). "Increased NF-κB-mediated transcriptional activity was detected in TRIM44-transfected breast cancer cells." (PMID 32503466, 2020). "It has been reported that the TRIM44 gene locus is frequently amplified in epithelial cancers, including breast cancer, and that TRIM44-amplified cancers likely have poorer outcomes." (PMID 28885545, 2017). "To further understand the biological functions of TRIM44 in breast cancer, we screened TRIM44 target genes by performing microarray analysis for MDA-MB-231 cells treated with siTRIM44 or siControl." (PMID 28885545, 2017). "In the present study, we demonstrated that high TRIM44 immunoreactivity (IR) is an independent poor prognostic factor in patients with breast cancer." (PMID 28885545, 2017). "Elevated NF-κB-mediated transcriptional activity was observed in TRIM44 transfected breast cancer cells compared to mock transfected cells." (PMID 28885545, 2017). "The present study further showed that TRIM44 is closely related to the NF-κB pathway in breast cancer cells, as exemplified by TRIM44 knockdown-mediated repression of p65 or IκBα phosphorylation." (PMID 28885545, 2017). "We performed an immunohistochemical study of TRIM44 protein in clinical breast cancer tissues from 129 patients." (PMID 28885545, 2017). "TRIM44 would play a role in the progression of breast cancer by promoting cell proliferation and migration, as well as by enhancing NF-κB signaling." (PMID 28885545, 2017). "In terms of breast cancer, genomic amplifications or gains of TRIM44 were shown, but protein expression in breast cancer tissues or functions of TRIM44 in breast cancer cells were not evaluated in the report." (PMID 28885545, 2017). "The pathophysiological role of TRIM44 in breast cancer was assessed by modulating TRIM44 expression in MCF-7 and MDA-MB-231 breast cancer cells." (PMID 28885545, 2017). "We next examined the relationship between TRIM44 IR and the clinical prognosis of breast cancer patients." (PMID 28885545, 2017). "Taken as a whole, this study indicates that TRIM44 has distinct relevance in the pathophysiology of breast cancer." (PMID 28885545, 2017). "It has been found that TRIM44 is overexpressed in a variety of tumors and is involved in malignant tumor progression, including colorectal cancer, esophageal cancer, renal cell carcinoma, and breast cancer." (PMID 34150336, 2021). "In a migration assay, we found that TRIM44 affected the motility of breast cancer cells." (PMID 28885545, 2017). "Our clinical study demonstrated that breast cancer patient outcomes are correlated with the immunoreactivity detected by the anti-TRIM44 antibody, which could be used as a potential biomarker to predict poor prognosis for survival of patients." (PMID 28885545, 2017). "Here, we examined TRIM44 protein expression in breast cancer specimens by immunohistochemistry." (PMID 28885545, 2017). "TRIM44 knockdown caused attenuated phosphorylation of the p65 subunit of NF-κB and NF-κB inhibitor α (IκBα) on TNFα stimulation in both MCF-7 and MDA-MB-231 breast cancer cells." (PMID 28885545, 2017). "We further investigated whether NF-κB signaling modulates the expression of potential TRIM44 target genes in breast cancer cells." (PMID 28885545, 2017). "Similarly, breast cancer patients showing TRIM44 amplification have a significantly poorer prognosis than patients with normal copy numbers." (PMID 27058415, 2016). "Then, we explored whether TRIM44 mRNA expression could also be a biomarker for breast cancer." (PMID 28885545, 2017).
breast cancer (continued). "Therefore, it is possible that the PI3K/Akt/mTOR pathway might be involved in the TRIM44-dependent NF-κB activation in breast cancer cells." (PMID 28885545, 2017). "In order to evaluate the biological functions of TRIM44 in human breast cancer cells, we transfected specific siRNAs for TRIM44 (siTRIM44-A/-B) in both ER-positive MCF-7 and ER-negative MDA-MB-231 breast cancer cell lines." (PMID 28885545, 2017). "Based on the breast cancer cohort of the METABRIC database, ~6% of the patients had TRIM44 amplifications or gains and had poorer prognosis than patients with normal copy number." (PMID 28885545, 2017). "The reporter assay revealed TRIM44 knockdown significantly impaired NF-κB-mediated transcriptional activity stimulated by tumor necrosis factor α (TNFα) in both MCF-7 and MDA-MB-231 breast cancer cells." (PMID 28885545, 2017). "In regard to tripartite motif-containing 44 (TRIM44), which is an atypical TRIM family protein lacking the RING finger domain, its pathophysiological significance in breast cancer remains unknown." (PMID 28885545, 2017).
esophageal cancer (8 papers, 2018 to 2022). A primary or metastatic malignant neoplasm involving the esophagus. "Furthermore, overexpression of TRIM44 has been reported to be associated with inhibition of apoptosis in esophageal cancer." (PMID 32503466, 2020). "Furthermore, overexpression of TRIM44 was reported to be associated with apoptosis inhibition in esophageal cancer." (PMID 29446253, 2018). "TRIM44 significantly enhances the proliferation, migration, and invasion of human esophageal cancer cells by participating in the AKT/mTOR signaling pathway and phosphorylation of its downstream target STAT3." (PMID 36249749, 2022). "TRIM44 facilitated proliferation, migration, and invasion in colorectal cancer, melanoma, esophageal cancer and hepatocellular carcinoma." (PMID 33391405, 2021). "In human esophageal cancer, TRIM44 was involved in the AKT/mTOR signaling pathway and STAT3 phosphorylation." (PMID 33391405, 2021). "TRIM44 promoted human esophageal cancer progression via the AKT/mTOR pathway." (PMID 31823782, 2019). "TRIM44 was also found to facilitate the EMT process by activating the Akt/mTOR pathway and thus promoting the metastasis of human esophageal cancer cells." (PMID 36249749, 2022). "The cell invasive and migratory properties of TRIM44 have been attributed to EMT in situations of hepatocellular carcinoma and human esophageal cancer." (PMID 33679655, 2021).
hepatocellular carcinoma (8 papers, 2018 to 2024). A malignant tumor that arises from hepatocytes. "TRIM44, in particular, is upregulated in several cancers, including head and neck squamous cell carcinoma, lung, prostate, ovarian, and hepatocellular carcinoma." (PMID 39273003, 2024). "Regarding chemotherapy resistance, only one publication showed that TRIM44 conferred the resistance of hepatocellular carcinoma cells to doxorubicin by regulating the NF-κB signaling pathway." (PMID 35541909, 2022). "Overexpression of TRIM44 promotes cell proliferation and enhances hepatocellular carcinoma cell invasion and migration." (PMID 34677810, 2021). "Previous studies have shown that high levels of TRIM44 induce cellular EMT in hepatocellular carcinoma (HCC) and non-small cell lung carcinoma (NSCLC)." (PMID 30922374, 2019).